CST3 (cystatin C)
Diseases named in the same sentence as CST3 in open-access papers (continued):
Sharing a sentence is not in itself a finding about the gene and the disease.
cognitive decline (19 papers, 2016 to 2026). "In the Cardiovascular Health Study, cystatin C was significantly associated with incident ischemic stroke and was a marker of poor outcome (shorter survival, cognitive decline and activities of daily living decline) after ischemic stroke in old adults." (PMID 37155257, 2023). "A multiple linear regression model was used to test the association between cystatin C and cognitive decline." (PMID 36518820, 2022). "Higher cystatin C levels have been associated with accelerated cognitive decline and cerebral white matter hyperintensities, which are markers of the brain aging process." (PMID 31528718, 2019). "Cystatin C is associated with cognitive decline in early-stage MSA." (PMID 39997046, 2025). "The objective was to determine whether cystatin C was independently associated with cognitive decline in patients with early-stage MSA." (PMID 36518820, 2022). "Our results suggested that higher baseline cystatin C levels could predict a higher risk of cognitive decline after accounting for potential confounders." (PMID 36518820, 2022). "However, the association between cystatin C and cognitive decline in patients with MSA remains largely unknown." (PMID 36518820, 2022). "Additionally, multiple linear regression model showed that baseline cystatin C levels were significantly associated with cognitive decline in early-stage MSA after adjusting for age, sex, educational years, disease duration, diagnosis subtype, OH, eGFR, and baseline MoCA score." (PMID 36518820, 2022). "However, the association between cystatin C and cognitive decline in patients with multiple system atrophy (MSA) remains largely unknown." (PMID 36518820, 2022). "K-means clustering was used to classify the longitudinal changes of Cystatin C. The long-term effects of Cystatin C on cognitive decline were evaluated, and subgroup analyses were performed in different populations." (PMID 41778039, 2026). "In univariable model baseline cystatin C, CKD-EPI eGFRcys, and all eGFRcre formulas were significantly associated with cognitive decline." (PMID 37052588, 2023). "Meanwhile, the higher serum cystatin C was an independent risk factor for PSCI in patients with acute mild ischemic stroke, which can provide early prediction of cognitive decline in the elderly." (PMID 36090853, 2022). "In non-diabetic individuals aged ≥65 years, cumulative Cystatin C increased the risk of cognitive decline." (PMID 41778039, 2026). "These high-risk genes dysregulated in more than one cell type, such as IGF1R, DDIT4, and CST3, may be potential targets for delaying the onset of cognitive decline and neurodegenerative diseases in the elderly." (PMID 40036868, 2025). "Another hypothesis is the anti-inflammatory properties of Cystatin C, which have demonstrated the ability to regulate immune response and mitigate oxidative stress, thus aiding in the prevention of cognitive decline." (PMID 37207178, 2023). "Our finding indicates that Cystatin C level may serve as a biomarker for cognitive decline in older adults." (PMID 37207178, 2023). "The findings of this study indicate that Cystatin C level may be a biomarker for cognitive decline in older adults." (PMID 37207178, 2023). "Our results suggested that cystatin C may serve as a potential biomarker of cognitive decline in patients with early-stage MSA." (PMID 36518820, 2022). "Our findings strengthen the evidence that serum cystatin C may be involved in modulating the clinical expression of cognitive decline." (PMID 35153722, 2021). "Altogether, our finding adds to the growing body of literature suggesting that cystatin C may modulate the clinical progression and cognitive decline in the disease and can be suggested as a therapeutic biomarker for the early detection of AD." (PMID 27756387, 2016). "Furthermore, the exogenous Cystatin C induces impairment of insulin signaling in hippocampal neurons, which could promote cognitive decline and AD development." (PMID 37342358, 2023).
cognitive decline (continued). "Furthermore, the association between cystatin C and cognitive decline has not been fully investigated in community-based older adults." (PMID 37207178, 2023). "Consequently, the total cystatin C effect on global cognitive decline was -0.29 per 1 lncysC increase, the cardiovascular BS-dependant cystatin C effect was -0.28 per 1 lncysC increase, and the proportion of the mediated cystatin C effect was 97% (P = 0.03)." (PMID 37052588, 2023). "Cystatin C level may be a biomarker for cognitive decline in older adults." (PMID 37207178, 2023). "Additionally, cystatin C was associated with cognitive decline in patients with MSA at the 1-year follow-up independent of eGFR." (PMID 36518820, 2022). "Thus, a 1-year prospective cohort study was performed to explore the association between cystatin C and cognitive function, as well as whether cystatin C could be a potential predictor of cognitive decline in patients with early-stage MSA." (PMID 36518820, 2022). "Encouragingly, proteins such as apolipoprotein A-I, apolipoprotein C-I and cystatin-C, which were identified through both univariate regression analyses and LASSO, are some of the most widely investigated plasma biomarkers for cognitive decline." (PMID 37658429, 2023). "A longitudinal study of cognitive decline in older adults used a panel of 8 blood-based markers, including APOE, plasma amyloid β 42/40 ratio, telomere length, serum glucose, cystatin C, C-reactive protein (CRP), interleukin-6 (IL-6), and albumin." (PMID 33946285, 2021). "After 11 years of follow-up, the 5 blood-based markers that correlated best with cognitive decline were APOE (present/absent), cystatin C, serum glucose, CRP, and IL-6." (PMID 33946285, 2021).
Cirrhosis (18 papers, 2012 to 2025). A chronic disorder of the liver in which liver tissue becomes scarred and is partially replaced by regenerative nodules and fibrotic tissue resulting in loss of liver function. "In this study, TSP-1, Galectin-3, and Cystatin-C were found to be independent risk factors for death in patients with cirrhosis, whereas Albumin and Prealbumin were protective." (PMID 40417691, 2025). "Previous studies have reported that age, plasma D-dimer level, serum cystatin C level, and total bilirubin level are associated with poor outcomes in cirrhosis patients." (PMID 32714387, 2020). "In conclusion, changes in serum cystatin C early in the course of AKI in patients with cirrhosis associate more strongly with the need for dialysis and mortality than do changes in serum creatinine." (PMID 24757564, 2014). "Biomarkers such as Thrombospondin-1 (TSP-1), Galectin-3 (Gal-3), and Cystatin C (Cys-C) have been studied for their roles in assessing liver fibrosis and predicting cirrhosis progression." (PMID 40417691, 2025). "The CKD-EPI equation that combines serum creatinine and cystatin C measurements shows the best performance for accurate estimation of GFR in cirrhosis, especially at advanced stages." (PMID 26627205, 2015). "The purpose of this study was to compare the association of changes in cystatin C and creatinine early in the course of AKI in patients with cirrhosis with a composite outcome of dialysis or death." (PMID 24757564, 2014). "We conducted a prospective multicenter study in patients with cirrhosis comparing changes in cystatin C and creatinine immediately following onset of AKI as predictors of dialysis and mortality during this early time period." (PMID 24757564, 2014). "In patients with cirrhosis, cystatin C has been shown to more accurately correlate with measured GFR than creatinine or creatinine based estimation equations." (PMID 24757564, 2014). "Recently, it, using cystatin C, one of the serum proteins, was effective for evaluating the renal function of patients with cirrhosis." (PMID 23326675, 2012). "Moreover, a recent meta-analysis in cirrhosis patients indicated that eGFR equations based on both creatinine and cystatin C were less biased than those based on creatinine alone, which overestimate GFR, and cystatin C alone, which tend to underestimate GFR." (PMID 37003973, 2023). "However, while Cystatin C-based estimation of GFR seems to be highly desirable in patients suffering from cirrhosis, it should be noted that there are several factors modifying both cystatin C and sCr levels." (PMID 38139297, 2023). "Novel biomarkers, such as cystatin C, may be considered as a surrogate marker for assessing kidney injury in patients with cirrhosis and AUD." (PMID 30188943, 2018). "Prospective trials indexing interventions to changes in cystatin are required to determine if routine monitoring of cystatin C in patients with cirrhosis and AKI may lead to improved outcomes." (PMID 24757564, 2014). "Cystatin C formulae may offer a simpler alternative to gold standard clearance methods for determining GFR in cirrhosis and appear to predict development of AKI when determined at 48 h prior to the insult." (PMID 23577724, 2013). "Some studies have shown that cystatin C may be a better assay for GFR estimation in the setting of cirrhosis and a 2006 study showed that serum cystatin C correlated better with iohexol-based GFR estimates than serum creatinine did." (PMID 23327592, 2013). "Although serum cystatin C determination could be a valuable tool in patients with cirrhosis for early diagnosis of moderately impaired renal function, further investigation is needed to clarify its effectiveness, for evaluating patients with decompensated cirrhosis." (PMID 23326675, 2012). "In patients with cirrhosis, GFR estimates are less biased and more precise with cystatin C than creatinine." (PMID 24757564, 2014).
Cirrhosis (continued). "Despite these attributes, cystatin C has been challenging to study in patients with cirrhosis and AKI due to the typical lack of a documented baseline value." (PMID 24757564, 2014). "In our study, the performance of urine NGAL as an early predictor of AKI was found to be superior to that of plasma cystatin C. This finding suggests that kidney tubular injury marker, rather than functional markers, may be more sensitive for early detection of AKI in advanced cirrhosis." (PMID 31601879, 2019). "Despite promising results with the use of cystatin C,Xirouchakis stated in a recent paper that the estimated GFR in cirrhosis is not better withcystatin C formulas compared to creatinine ones." (PMID 23805157, 2013).
depression (18 papers, 2014 to 2026). "A cohort study involving 1,440 Chinese seniors over 60 identified a detrimental association between elevated serum cystatin C levels and heightened depression risk." (PMID 40256164, 2025). "This is likely because patients with depression are often accompanied by increased levels of inflammation, and inflammatory cells are associated with increased levels of cystatin C, leading to underestimated CCR levels." (PMID 40454388, 2025). "This suggests a possible association between NK cells, cystatin C, and the development of depression due to inflammation." (PMID 37673891, 2023). "They computed the risk of depression by using modified Poission regression models, found that the association between serum cystatin C levels and the risk of depression remained significant after adjusting for multiple covariance." (PMID 35722576, 2022). "A study which enrolled 1,440 Chinese elders (>60 years old) found a harmful relationship between high serum cystatin C levels and risk of depression." (PMID 35722576, 2022). "Another prospective cohort study of 11,847 Chinese people (>45 years old) demonstrated that high levels of serum cystatin C were associated with an increased risk of depression." (PMID 35722576, 2022). "Research reveals that patients experiencing depression exhibit considerably higher cystatin C levels compared to healthy individuals, which may be linked to immunological processes." (PMID 40256164, 2025). "Notably, depression, cystatin C, and FEV1 have been previously associated with frailty in a prior study of physiologic determinants of frailty independent of multimorbidity." (PMID 41426610, 2025). "Serum cystatin C (Cys C) exerts biological functions in several aspects including bioactivity and neurophysiology, and it may affect the risk of depression in a number of ways." (PMID 39916347, 2025). "However, most investigations by now laid the emphasis on the relationship about higher cystatin C concentration appear to present with high risk of depression." (PMID 35722576, 2022). "Recent studies have explored the link between high serum cystatin C levels and psychiatric disorders, particularly depression." (PMID 40256164, 2025). "This study identified 6 robust predictors of ADL dysfunction in the older adults, namely CESD-10 depression score, number of painful areas, left-hand grip strength, 2.5-m walking time, weight, and cystatin C levels." (PMID 40537082, 2025). "Recent scholarly interest has increased in the relationship between serum cystatin C levels and central nervous system disorders, including Alzheimer’s, Parkinson’s, and depression." (PMID 40256164, 2025). "The final model incorporated 6 predictors: the 10-item Center for Epidemiologic Studies Depression Scale depression score, number of painful areas, left-hand grip strength, 2.5-m walking time, weight, and cystatin C level." (PMID 40537082, 2025). "In our research, we showed that patients with higher depression events correlated with higher serum levels of cystatin C, then had an increased CES-D score at baseline." (PMID 35722576, 2022). "Several researchers have already evaluated the potential link between cystatin C levels and depression." (PMID 35722576, 2022). "We indicate that cystatin C should be monitored in the pathogenesis of depression among all the kidney function markers." (PMID 35722576, 2022). "Another possible mechanism is that cystatin C is close to oxidative stress, which can play a significant role in the process of depression." (PMID 35722576, 2022). "The last possible mechanism is that cystatin C is related to oxidative stress, which plays an important role in depression." (PMID 34789194, 2021). "We defined impaired kidney function as the cystatin C-based estimated glomerular filtration rate (eGFRcysC) < 60 ml/min/1.73 m2, and depressive symptoms as a score ≥ 5 on the 15-item Geriatric Depression Scale." (PMID 30400830, 2018).
depression (continued). "Cystatin C has various biological functions potentially influencing depression development." (PMID 40256164, 2025). "In comparison to depressive episodes, manic episodes might correlate with a more pronounced inflammatory response, which could influence cystatin C levels." (PMID 40256164, 2025). "Although high cystatin C levels have been linked with major depressive disorder, no studies, to the best of our knowledge, have demonstrated an association between cystatin C and bipolar disorder." (PMID 39006413, 2024). "In the prospective Cardiovascular Health Study, cystatin C was associated with depression among participants without CKD at baseline but this was a borderline association after adjusting for both demographic and clinical measures." (PMID 25219531, 2014). "Last but not least, apoptosis may be an important risk factor for depression, it can also influence on the level of Cystatin C by changing the concentration of active caspinase-9 protein." (PMID 35722576, 2022). "We speculate that cystatin C may play an important role in the pathogenesis of depression." (PMID 34789194, 2021). "This strongly contrasts with our main matched-control analysis, where only three traits lacked a nominally significant effect: recurrent depressive disorder, anemia, and cystatin C." (PMID 39332408, 2024). "By testing a series of behavioral experiments, we also found that the aging Cst3-KO gerbils showed a decrease of social discovery and depression trend (data not shown), indicating that CST3 may have multiple protective roles in brain." (PMID 32733872, 2020).
ischemic stroke (18 papers, 2014 to 2025). A stroke disorder caused by obstruction of blood flow to the brain, due to thrombotic (local blood clot formation) or embolic (due to a blood clot or other material traveling from another site) event. "Meta-analytic data consistently demonstrate an association between elevated cystatin C levels and an increased incidence of ischemic stroke, particularly in acute-phase and subclinical cerebral infarction subgroups." (PMID 40941489, 2025). "A prospective pooled analysis using six cohorts summarized that cystatin C is significantly associated with ischemic stroke." (PMID 38681764, 2024). "A study among the European population found that cystatin C concentrations were associated with ischemic stroke after adjusting for traditional risk factors." (PMID 38681764, 2024). "The discrepancy between cystatin C- and creatinine-based eGFR for detecting risk of ischaemic stroke was greater in women than in men." (PMID 37641551, 2023). "High expression and mutations in the CST3 (Cystatin C) gene have been reported in systolic HF, ischemic stroke, and CAD." (PMID 34774109, 2021). "The measurement of cystatin C may enhance risk stratification for ischaemic stroke and improve clinical treatment in a general population, especially for women." (PMID 39544376, 2024). "Enhanced measurement of cystatin C may improve risk stratification for ischaemic stroke and major bleeding and clinical treatment decisions in a general population setting, particularly for women." (PMID 37641551, 2023). "Enhanced measurement of cystatin C may improve risk stratification and clinical treatment decisions for ischaemic stroke and major bleeding in a general population setting, particularly for women." (PMID 37641551, 2023). "Enhanced measurement of cystatin C may improve risk stratification for ischaemic stroke, major bleeding and clinical treatment decisions in a general population setting, but particularly for women." (PMID 37641551, 2023). "A meta-analysis of nine cross-sectional studies found that patients of ischemic stroke had distinctly increased serum cystatin C concentrations compared to controls." (PMID 38681764, 2024). "Age, pulse, waist circumference, education level, β2‐microglobulin, homocysteine, cystatin C, folate, free triiodothyronine, platelet distribution width, QT interval, and QTc interval were significant induced predictors of ischemic stroke." (PMID 37934082, 2023). "As a subgroup analysis of CNSR-III, two loci of the CST3 gene (rs13038305 and rs911119) were analyzed in 3,833 ischemic stroke patients." (PMID 34721268, 2021). "Previous studies also report serum cystatin C (not incorporated into eGFR) to be associated with ischaemic stroke, though raw values are more difficult to interpret without acknowledging the influence of kidney function on the concentration in serum." (PMID 37641551, 2023). "For example, CST3 (cystatin C), an extracellular space protein, was used as a biomarker to evaluate kidney function (glomerular filtration rate, GFR) (NCT00300066 in ClinicalTrials.gov database) and to predict the risk of ischemic stroke (NCT00479518)." (PMID 36814924, 2023). "With the improvement of electronic medical record networking system and the development of mobile laboratory, biomarkers which had been proved to be correlated with ischemic stroke, such as D-dimer, Cystatin C and low-density Lipoprotein can be added in the ANN model." (PMID 29997494, 2018). "Our results showed that cystatin C may be a more sensitive indicator to detect the severity of CMBs compared to the estimated GFR or microalbumin/creatinine ratio in patients with ischemic stroke." (PMID 24925313, 2014).